EZH2 (enhancer of zeste 2 polycomb repressive complex 2 subunit)
Diseases named in the same sentence as EZH2 in open-access papers (continued):
Sharing a sentence is not in itself a finding about the gene and the disease.
colon carcinoma (continued). "Analyses of colon cancers representing different degrees of histological dedifferentiation (increasing from G1–G3) revealed a trend for a further increase of EZH2 expression for less differentiated cancers, which, however, was not statistically significant." (PMID 21765901, 2011). "Taken together, these results indicate that EZH2 depletion induces cell cycle arrest in the G1 phase and inhibits the growth of colon cancer cells." (PMID 21765901, 2011). "To validate the antiproliferative effect of EZH2 inhibition in colon cancer cells by an independent method, we performed colony formation assays." (PMID 21765901, 2011). "In the present study, we show that EZH2 depletion in colon cancer cells (i) reduces cell cycle progression at the G1/S boundary, (ii) decreases cell numbers in short term growth assays, and (iii) blocks cell growth in long-term colony formation assays." (PMID 21765901, 2011). "In order to get insight into the spectrum of genes, which are affected by EZH2 depletion in colon cancer cells, we performed whole genome transcriptome analyses in DLD1 and LoVo cells." (PMID 21765901, 2011). "The overlap consisted of 139 genes that were affected by EZH2 depletion in both colon cancer cell lines (100 upregulated, 39 downregulated)." (PMID 21765901, 2011). "In order to investigate the expression of EZH2 in colon cancer cells in vitro, we analyzed a panel of twelve tumor-derived colon cancer cell lines by immunoblotting and qRT-PCR." (PMID 21765901, 2011). "Our findings thus indicate that EZH2 stimulates the proliferation of colon cancer cells, as has been reported for several other cancer entities." (PMID 21765901, 2011). "In order to identify possible target genes affected by EZH2 depletion in colon cancer cells, transcriptome analyses were performed." (PMID 21765901, 2011). "Whole genome transcriptome analyses identified cellular genes affected by EZH2 depletion in colon cancer cell lines." (PMID 21765901, 2011). "Since p27 acts at the G1/S transition - which we found to be affected by EZH2 silencing in colon cancer cells - and since p27 levels are frequently low in colon cancers, we tested a possible correlation between EZH2 and p27 levels in vivo and in vitro." (PMID 21765901, 2011). "Despite the high biomedical significance of this tumor, investigations of the EZH2 status and function in colon cancer cells are sparse and partly contradictory." (PMID 21765901, 2011). "Both EZH2-targeting siRNAs led to a clear reduction of the colony formation capacity of all tested colon cancer cell lines versus control siRNA-treated cells." (PMID 21765901, 2011). "RNAi-mediated inhibition of EZH2 expression led to a significant reduction of cell numbers, which was clearly visible 48–72 hours following transfection of synthetic siRNAs, indicating that EZH2 silencing results in growth inhibition of colon cancer cells." (PMID 21765901, 2011). "In colon cancer stages II and III, a high EZH2 index was significantly associated with a better RFS (P=0.041 by the log-rank test), and with a trend for better CSS (P=0.069)." (PMID 19773751, 2009). "Unexpectedly, and in line with our EZH2 data, Ki-67 protein expression in >40% of the tumour cells was also associated with a better RFS in colon cancer stages II and III." (PMID 19773751, 2009). "In colon cancer, strong EZH2 expression (P=0.041) and high proliferation (⩾40%; P=0.001) were both associated with better relapse-free survival (RFS)." (PMID 19773751, 2009). "In a recent study, we have shown that the curcumin-induced cytotoxic effect against colon cancer cells correlated with the downregulation of methyltransferases such as enhancer of Zeste 2 Polycomb repressive complex 2 Subunit (EZH2), G9a, and mixed lineage leukemia protein-1 (MLL-1)." (PMID 40807229, 2025).
colon carcinoma (continued). "Our recent work showed that low-dose DNMT inhibitor (DNMTi) treatment sensitizes colon cancer cells to EZH2 inhibitors (EZH2i), synergistically upregulating tumor suppressor genes (TSGs) and transposable elements through activation of the calcium-calcineurin-NFAT signaling pathway." (PMID 41000734, 2025). "In addition, knocking down USP22 can potentially enhance the therapeutic efficacy of EZH2 inhibitors on colon cancer." (PMID 38520088, 2024). "High EZH2 expression was shown to be substantially correlated with tumor stage, tumor size, histological differentiation, and lymph node metastasis of colon cancer, according to an investigation of the relationship between clinicopathological characteristics and EZH2 expression." (PMID 37337955, 2023). "This is an important finding as it suggests that DCAF1 and EZH2 inhibitors may be combined to achieve a more favorable therapeutic index for colon cancer patients by establishing distinct epigenetic states at growth regulatory genes." (PMID 37069142, 2023). "Furthermore, we provide evidence that pharmacologically targeting DCAF1 and EZH2 in organoid and xenograft models is sufficient to impair their ability to induce oncogenic gene silencing as well as colonic tumor growth." (PMID 37069142, 2023). "The observed effect of B32B3 is suggestive of EZH2-targeted action of DCAF1 in colon cancer cells." (PMID 37069142, 2023). "Also, knockdown of p38 and treatment with the p38 specific inhibitor SB202190 failed to generate any detectable changes in the levels of EZH2T367p and EZH2 in colon cancer cells." (PMID 37069142, 2023). "However, the inability of CHX to decrease EZH2 protein levels in EZH2T367D-transfected, EZH2-depleted SW620 cells supported the view that DCAF1-mediated T367p is sufficient to generate the higher stability of EZH2 in colon cancer cells." (PMID 37069142, 2023). "The effect of EZH2 upon colon cancer cell proliferation was measured via CCK-8 assay." (PMID 38048186, 2023). "Thus, our study not only identifies EZH2T367p as a biomarker for the prediction of colon cancer but also provides the evidence that targeting DCAF1 kinase activity toward EZH2 is a promising strategy for tackling colon cancer development." (PMID 37069142, 2023). "Moreover, much higher levels of DCAF1 protein in human colon tumor samples and a strong correlation between protein levels for DCAF1 and EZH2 are further indicative of a DCAF1 role in enhancing EZH2 protein stability in colon cancer cells." (PMID 37069142, 2023). "Similarly, it was noted that EZH2 overexpression triggered the elevation of colon cancer cell senescence." (PMID 35668081, 2022). "Interestingly, tumor cells respond more likely to EZH2 inhibitors and they have been applied in treatment of colon cancer (stage II and III)." (PMID 35236381, 2022). "MiRNA and EZH2 interaction is a determining factor for colon cancer progression." (PMID 35236381, 2022). "In addition, silencing expression of the epigenetic regulator EZH2 (enhancer of zeste homolog 2) led to the downregulation of FAM57A transcript levels in colon cancer cells in large scale transcriptome analyses." (PMID 36291175, 2022). "In colon cancer, EZH2 but not H3K27me3 expression is associated with progression from adenoma to carcinoma." (PMID 35186711, 2021). "Using the APCmin/+ and AOM/DSS models, we showed that the deletion of the EZH2 gene significantly inhibited the occurrence of colon cancer, indicating a cancer-promoting function of EZH2 in CRC; these results were consistent with the function of EZH2 in other solid cancers." (PMID 34671029, 2021). "ROR-AS1/EZH2 inhibits the apoptosis of colon cancer by facilitating H3K27me3 on the DUSP5 promoter." (PMID 33050646, 2020).
colon carcinoma (continued). "Mechanistically, we provide evidences that the O-GlcNAcylated form of EZH2 prevents the transcription of UNC5A in human colon cancer cells through aberrant O-GlcNAcylation and abnormal targeting of the PRC2 complex onto its promoter, thus linking nutrition to downregulation of UNC5A in CRC." (PMID 33126652, 2020). "Additionally, EZH2 has been found to have a crucial role in facilitating the tumorigenesis of colon cancer." (PMID 32308561, 2020). "Similarly, in response to IL6, dimethylation of STAT3 at lysine 49 by EZH2 also promotes transcription of STAT3 targets in colon cancer." (PMID 33327550, 2020). "By carefully evaluating the opposing data in the literature about the prognostic value of EZH2 in colon cancer, we recognized marked differences in the study designs that may contribute to these controversies." (PMID 31317325, 2019). "Interestingly, both intestinal and colonic tumors exhibited elevated levels of EZH2 and β-catenin staining, respectively." (PMID 31040926, 2019). "Interestingly, we found a significant decrease in EZH2 staining at the invasion front of colon tumors in our study." (PMID 31317325, 2019). "Previous study demonstrated that down-regulation of methyltransferase EZH2 may induce apoptosis in colon cancer cells, which is consistent with our results showing that mancozeb increased H3K27 methylation levels and induced apoptosis in oocytes." (PMID 28031523, 2017). "The significant node of Ezh2 and its TFs such as E2f1, Hsfy2, and Nfyb may show the potential therapeutic effect on colon cancer." (PMID 28588641, 2017). "Ezh2 has been proposed to be therapeutic target for colon cancer intervention." (PMID 28588641, 2017). "To examine whether EZH2 suppressed miR-31 expression, we knocked down EZH2 mRNA by siRNAs in colon cancer cell lines and measured the resulting miR-31 expression." (PMID 26871294, 2016). "In addition, EZH2 can control cofilin activity and, consequently, the actin cytoskeleton structure that regulates the expression of integrin alpha 2 in colon cancer cells." (PMID 27248655, 2016). "Notably, the use of EZH2 inhibitor in colon cancer cells was reported to restore WNT/β-catenin activity." (PMID 27494834, 2016). "In order to determine whether EZH2 is required for growth of CRC or one of its subtypes, we treated the 20 colon cancer organoid lines with the EZH2 inhibitor GSK126." (PMID 27634879, 2016). "Therefore, EZH2 plays an important role in the proliferation and metastasis of colon cancer cells, potentially by acting as a mediator of miR-506 function." (PMID 26452129, 2015). "Furthermore, a Matrigel invasion assay and a wound-healing assay indicated that silencing EZH2 expression inhibited colon cancer cell invasion and migration, respectively." (PMID 26452129, 2015). "However, in colon cancer stem cells the treatment with EZH2 inhibitor DZNep actually increased PTEN expression, decreased p-AKT expression and induced cell apoptosis." (PMID 25141911, 2014). "In comparison to colon adenomas, EZH2 expression was significantly increased in colon carcinomas." (PMID 21765901, 2011). "Additional work is required to analyze the exact mechanisms by which EZH2 may alter the expression of these genes and to study in detail their possible contribution to the growth deregulation of colon cancer cells." (PMID 21765901, 2011). "Here, we investigated a possible role of EZH2 for the growth control of colon cancer cells." (PMID 21765901, 2011). "In view of our findings that EZH2 promotes cell proliferation and stimulates G1/S cell cycle progression of colon cancer cells, we addressed the question whether p27 is repressed by EZH2 in colon cancer as well." (PMID 21765901, 2011). "In our study, a high EZH2 index was associated with a better RFS in colon cancer stages II and III, but not in rectal cancer." (PMID 19773751, 2009). "Previous studies demonstrated that EZH2 could silence the expression of WNT5A in colon cancer." (PMID 38566211, 2024).
colon carcinoma (continued). "Furthermore, our preclinical studies using organoid and xenograft models revealed that EZH2 requires phosphorylation for its oncogenic function, which may have therapeutic implications for gene reactivation in colon cancer cells." (PMID 37069142, 2023). "Thus, a reproducible and time efficient method for EZH2 scoring could help to standardize the measurement of EZH2 staining patterns and to establish EZH2 as a reliable biomarker in colon cancer." (PMID 31317325, 2019). "Thus, our results suggest that high EZH2 expression may be involved in the progression of colon cancer, and serve as a potential biomarker, as well as treatment target for human colon cancer patients." (PMID 27882937, 2016). "In addition, we demonstrated that the knockdown of EZH2 by siRNAs increased miR-31 expression in colon cancer cell lines, suggesting that negative EZH2 expression causes miR-31 upregulation in the progression of SSA/Ps." (PMID 26871294, 2016). "The finding in our study that EZH2 contributes to the proliferation of colon cancer cells extends the spectrum of tumor entities that may therapeutically benefit from EZH2 inhibition to colon cancer." (PMID 21765901, 2011). "Immunohistochemical results showed that compared with normal colon tissues, MSI2, EZH2, and NCL were significantly higher expressed in colon cancer tissues except TERT." (PMID 40535805, 2025). "To test the contribution of EZH1 to H3K27 methylation state, we selected RKO out of a panel of colon cancer cell lines, as it has high expression of both EZH1 and EZH2 at the protein level." (PMID 41000734, 2025). "Researchers discovered that co-exposure to low-dose DNMT inhibitors (DNMTi) and inhibitors of the Enhancer of Zeste Homolog 2 (EZH2, a catalytic subunit of the histone methyltransferase Polycomb repressive complex 2 (PRC2)) sensitizes colon cancer cells." (PMID 39908270, 2025). "By contrast, the deubiquitinating enzyme USP22 promotes PD-L1 stabilization in colon cancer (COAD), while EZH2 inhibits USP22 transcription via H3K27me3, leading to PD-L1 degradation." (PMID 39080807, 2024). "To further reveal the global impacts of EZH2 functional suppression on colon tumor cells, we conducted transcriptome analysis of HCT116 colon cancer cells treated with Taz." (PMID 38520088, 2024). "As for colon carcinoma cells HCT116 and HT29, their proliferation, invasion and migration were prominently decreased after the EZH2 down-regulation, as shown in CCK8 and monoclonal proliferation experiments, scratch wound assay, and invasion assay." (PMID 38048186, 2023). "Therefore, EZH2 may become a promising target for the clinical therapy of colon carcinoma." (PMID 38048186, 2023). "Toward this end, we treated SW620 colon cancer cells with the proteasome inhibitor MG132 for 12 h, and evaluated its impact on EZH2 protein levels by Western blotting." (PMID 37069142, 2023). "The importance of DCAF1 with respect to the observed interaction was further confirmed by the finding that DCAF1 knockdown almost completely abrogates the ability of EZH2 to interact with EED and SUZ12 in colon cancer cells." (PMID 37069142, 2023). "FXR is expressed in colon cancer cells at variable levels; however, an inverse correlation was observed between FXR and EZH2 expression." (PMID 35449124, 2022). "Overexpression of miRNA-101 inhibits EZH2 signaling post-transcriptional to suppress EMT, leading to colon cancer metastasis impairment." (PMID 35236381, 2022). "We firstly assessed the IC50 values of colon cancer cells and FHC cells response to EZH2 inhibitor GSK126." (PMID 35449124, 2022). "The clinical correlation between EZH2 and FXR in CRC was explored in the tissue microarrays containing 90 pairs of colon cancer by IHC staining (cohort I)." (PMID 35449124, 2022). "TCGA database mining also supported an inverse correlation between EZH2 and FXR in the patients with colon cancer." (PMID 35449124, 2022).
colon carcinoma (continued). "To identify the interaction specificity between EZH2/JARID2 and lncRNAs, we re-analyzed the CLIP-seq of EZH2 in mouse ESC, and the CLIP-seq of EZH2 in colon cancer HCT-116 cells." (PMID 36578923, 2022). "Drugs targeting EZH2 has been shown to promote the secretion of Th1-type chemokine and subsequent local infiltration of CD8+ T cells in ovarian and colon cancer." (PMID 31727135, 2019). "To mirror-image the EZH2 status at the tumor invasion front, we treated HCT116 colon cancer cells with the EZH2 inhibitor 3-Deazaneplanocin A (DZNep) and studied the growth of in ovo xenografts in the chorioallantoic membrane (CAM) assay." (PMID 31317325, 2019). "It has been shown in the colon cancer cell line HT-29-M6 that both SNAI1 and EZH2 were required to recruit PRC2 on the promoter of CDH1, and that EZH2 and SNAI1 stabilized each other on this promoter." (PMID 34991274, 2018). "In lung and colon cancer, Jarid2 is involved in EMT process induced by TGF-β through EZH2-mediated transcriptional repression of CDH1 and microRNA-200 family genes." (PMID 28445934, 2017). "We were interested in the degree of co-expression of EzH2, p-p65 and MUC1 in colon cancer compared to a healthy colon or benign disease." (PMID 29285251, 2017). "Analysis of human colon cancer tissues microarray showed that hypoglycosylated MUC1, phospho-p65 and EzH2 are co-expressed in colon adenocarcinoma." (PMID 29285251, 2017). "In this work, we used human colon cancer cells to check the role of EZH2 in the antitumor effect of LDM, and found that EZH2 mediates the cellular senescence through regulating p21 expression." (PMID 27882937, 2016). "UNC1999 is a novel SAM-competitive EZH2/EZH1 inhibitor that has demonstrated efficacy in several cancer models such as leukemia, multiple myeloma and colon cancer." (PMID 27449082, 2016). "Here, we aim to study the role of EZH2 in LDM-induced senescence, as well as in the cytotoxicity of LDM in human colon cancer cells." (PMID 27882937, 2016). "EZH2 has been identified as a downstream effector of PI3K/AKT pathway, and its depletion inhibits invasion and EMT in metastatic colon cancer cells." (PMID 25141911, 2014). "In colon cancer stages II and III, there were trends for better RFS (P=0.077) and CSS (P=0.085) with a high EZH2 index in patients receiving adjuvant chemotherapy, but not in patients with no adjuvant therapy." (PMID 19773751, 2009). "Consequently, colon cancer cells with high levels of EZH1 respond differentially to dual EZH1/2 and EZH2-selective inhibitors when combined with DNMTi." (PMID 41000734, 2025). "In addition to linking methylation with the expression of oncogenic molecules, here we show that c-Myc in turn regulates epigenetics in colon cancer cells, being able to sustain not only the expression of MLL-1 but also that of EZH2." (PMID 40807229, 2025). "EZH2-OE is the opposite trend to si-EZH2; The EZH2 gene may target regulatory RUNX3 regulation via that Wnt/β-catenin signaling pathway, hence affecting colon carcinoma cell proliferation, invasion, migration, and apoptosis." (PMID 38048186, 2023). "Apart from EZH2 and RUNX3 genes expressions, proteins from colon cancer tissues and healthy tissues were histologically examined by our project group using immunohistochemical method and real time fluorescence quantitative reverse transcription-polymerase chain effect." (PMID 38048186, 2023). "We therefore next asked whether colon cancer cells are more responsive to the combination of DCAF1 inhibitor B32B3 and EZH2 inhibitor Tazemetostat (Taz)." (PMID 37069142, 2023). "Recently, EZH2 was found to be a target substrate for USP7, and USP7 deubiquitinates and stabilizes EZH2 and promotes cell migration, invasion, and sphere-forming potential in prostate and colon cancer cells." (PMID 37762082, 2023). "Henein, we observed a negative clinical correlation between FXR and EZH2 expression in colon cancer tissues." (PMID 35449124, 2022).